DNAJC15 (DnaJ heat shock protein family (Hsp40) member C15)
Description:
Negative regulator of the mitochondrial respiratory chain. Prevents mitochondrial hyperpolarization state and restricts mitochondrial generation of ATP (By similarity). Acts as an import component of the TIM23 translocase complex. Stimulates the ATPase activity of HSPA9.
Synonyms: MCJ; DNAJD1; HSD18
Tractability: Antibody: UniProt predicts a signal peptide or a membrane-spanning region.
Gene: Protein-coding gene on chromosome 13 (43,023,203 to 43,114,213, forward strand). Ensembl gene ENSG00000120675.
Subcellular location: Mitochondrion inner membrane
Gene Ontology:
Molecular function: protein binding; ATPase activator activity
Biological process: intracellular protein transport; protein import into mitochondrial matrix
Cellular component: mitochondrion; mitochondrial inner membrane; PAM complex, Tim23 associated import motor; TIM23 mitochondrial import inner membrane translocase complex
Genetic constraint (gnomAD): Loss-of-function variants: 25 observed, 21.29 expected, observed/expected ratio (o/e) 1.17, 90% interval 0.86 to 1.63. The upper end of that interval is the gene's LOEUF score, 1.63, which puts it in group 6 of 6, group 1 being the genes least tolerant of losing a copy. Missense variants: 203 observed, 180.34 expected, observed/expected ratio (o/e) 1.13, 90% interval 1 to 1.26. Synonymous variants: 75 observed, 63.3 expected, observed/expected ratio (o/e) 1.18, 90% interval 0.98 to 1.44.
Homologues: Orthologues: chimpanzee DNAJC15 (99% identical), macaque DNAJC15 (94% identical), rabbit DNAJC15 (85% identical), guinea pig DNAJC15 (81% identical), pig DNAJC15 (81% identical), mouse Dnajc15 (77% identical), dog DNAJC15 (68% identical), tropical clawed frog dnajc15 (68% identical), zebrafish dnajc15 (63% identical), rat Dnajc15 (61% identical), Drosophila melanogaster CG7394 (43% identical), Caenorhabditis elegans dnj-21 (42% identical). Paralogues in human: DNAJC19 (45% identical).
Diseases named in the same sentence as DNAJC15 in open-access papers:
DNAJC15 is named in the same sentence as 40 diseases in open-access papers, as found by Europe PMC text mining. Sharing a sentence is not in itself a finding about the gene and the disease. The quoted sentences say what the papers report.
breast carcinoma (9 papers, 2010 to 2024). "In agreement with that, it was reported that the deficiency in MCJ/DnaJC15, which negatively regulates SC formation, is associated with multidrug resistance in mouse and human breast cancer." (PMID 34747989, 2021). "ETV7 also mediates the resistance to doxorubicin through downregulation of DNAJ heat shock protein family (Hsp40) member C15 (DNAJC15) in breast cancer." (PMID 38200280, 2024). "MCJ, also known as DnaJC15, is a transmembrane protein that is found in the inner mitochondrial membrane, whose absence leads to increased complex I activity and mitochondrial respiration in breast cancer, immune cells, and the liver." (PMID 33997750, 2021). "Indeed, DNAJC15/MCJ is frequently hyper-methylated in multiple types of human cancer, including malignant pediatric tumors, neuroblastoma, Wilm’s tumor, melanoma, and breast cancer." (PMID 34948322, 2021). "Reduced expression of DNAJC15/MCJ is also correlated with increased drug resistance, as well as increased levels of c-JUN protein and its downstream target ATP binding cassette subfamily B member 1 (ABCB1)/multiple drug resistance 1 (MDR1), in ovarian and breast cancers." (PMID 34948322, 2021).
ovarian carcinoma (6 papers, 2010 to 2025). A malignant neoplasm originating from the surface ovarian epithelium. "Recently, it has been proposed that the loss of DNAJC15 correlates with cisplatin (CDDP)-resistance onset in ovarian cancer (OC), suggesting this protein as a potential prognostic factor during OC progression." (PMID 39809321, 2025). "Moreover, they linked loss of DNAJC15 expression to resistance to the chemotherapeutic drug cisplatin in an ovarian carcinoma cell line as well as in ovarian carcinoma patients." (PMID 20544021, 2010). "Concomitantly, high DNAJC15 expression levels have been associated with increased responsiveness to paclitaxel, topotecan and cisplatin (CDDP) in ovarian cancer (OC)." (PMID 39809321, 2025). "In case of the ovarian carcinoma cell lines OVCAR-5, OVCAR-4 and NCI/ADR-RES, the methylation status of CGIs associated with the genes ABCB1, BRCA1, CDH1, DNAJC15, and SULF2 was connected to the expression of the genes." (PMID 20544021, 2010). "Here we provided additional evidence for the epigenetic regulation of DNAJC15 expression in breast and ovarian carcinoma cell lines and further demonstrated the correlation of the gene's loss-of-expression with resistance to doxorubicin." (PMID 20544021, 2010). "An overlapping set of seven genes (ABCB1, APC, BRCA1, CDH1, DNAJC15, HIC1 and SULF2) displayed the same methylation changes in the examined set of ovarian carcinoma cell lines." (PMID 20544021, 2010).
Hepatic steatosis (4 papers, 2020 to 2025). Steatosis is a term used to denote lipid accumulation within hepatocytes. "Indeed, it has been reported that DNAJC15 knock-out mice showed increased resistance to hepatic steatosis induced by a high-fat diet as model for non-alcoholic fatty liver disease." (PMID 39809321, 2025).
melanoma (3 papers, 2021 to 2024). A malignant, usually aggressive tumor composed of atypical, neoplastic melanocytes. "Regulation of DNAJC15 expression involves gene hypermethylation in cancer cells, which has been demonstrated in several cancer cell types, including brain, ovarian, and melanoma." (PMID 39728572, 2024).
Arthritis (1 paper, 2021). Inflammation of a joint. "Lyz1, Dnajc15, Nfkbia, Cxcl12, Ccl21a, and Cxcl13 are considered to be arthritis-associated gene." (PMID 33752715, 2021).
cerebellar ataxia (1 paper, 2014). A neurological syndrome characterized by clumsy and uncoordinated movement of the limbs, trunk, and cranial muscles. "Clearly, DNAJC19 and another mitochondrial J protein, DNAJC15, are not redundant as DnaJC15 does not rescue DnaJC19 mutations that lead to dilated cardiomyopathy and cerebellar ataxia." (PMID 25071450, 2014).
Obesity (1 paper, 2024). Accumulation of substantial excess body fat. "A total of 12 significant SNPs associated with BMI were identified, of which 7 SNPs were also significantly associated with obesity, including rs1337406 (WLS), rs673612 (NTNG1), rs4449107 (FAM84A), rs9820485 (STAG1), rs73247924 (CCKAR), rs2083069 (ACADSB), and rs4942190 (DNAJC15)." (PMID 38807991, 2024).
Stroke (1 paper, 2023). Sudden impairment of blood flow to a part of the brain due to occlusion or rupture of an artery to the brain. "Six proteins (AGFG2, C1QTNF1, CHIT1, DNAJC15, FTL, and OLR1) have been reported to be implicated in other neurodegenerative diseases such as AD, ALS, or stroke, but not in PD." (PMID 37422510, 2023).
type 2 diabetes (1 paper, 2011). "Dnajc15 has been suggested to be involved in pronephros development in Xenopus embryos, and Camk1d has been associated with type 2 diabetes." (PMID 21408189, 2011).
tumor (17 papers, 2010 to 2026). "Particularly, the unveiling of a DNAJC15-linked ferroptosis activation mechanism could be useful for the identification of additional molecular determinants involved in this cell death pathway, which has recently been shown to contribute to tumour suppression." (PMID 39809321, 2025). "We have recently published a novel mechanism of ETV7-mediated resistance to the chemotherapeutic agent Doxorubicin which involves the downregulation of DNAJC15 tumor suppressor leading to an increased expression of ABCB1 efflux pump." (PMID 34315857, 2021). "DNAJC15/MCJ potentially acts as a tumor suppressor by promoting the release of pro-apoptotic molecules through the mitochondrial permeability transition pore complex." (PMID 34948322, 2021). "The identified genes are involved in drug transport and detoxification (ABCB1, DNAJC15, GSTP1, RAB6C), DNA damage repair (BRCA1) as well as tumor cell proliferation/invasion (APC, CDH1, ESR1, HIC, PLAU, RASSF1, SULF2, TGM2)." (PMID 20544021, 2010). "Methylation-controlled J protein (MCJ; also known as DNAJC15) is a negative regulator of mitochondrial respiration, but its role in tumor metabolism remains unclear." (PMID 42113076, 2026).
cancer (14 papers, 2015 to 2026). A tumor composed of atypical neoplastic, often pleomorphic cells that invade other tissues. "We further demonstrate that the loss of methylation-controlled J protein (MCJ) (also named DnaJC15), an endogenous negative regulator of mitochondrial respiration, in chemoresistant cancer cells boosts their ability to produce ATP from mitochondria and fuel ABC transporters." (PMID 33990571, 2021). "It has been previously reported that DNAJC15 overexpression can increase the apoptotic cell death sensitivity in different cancer models upon CDDP treatment possibly due to the opening of MPTP." (PMID 39809321, 2025). "Since resistance to antiblastic therapy is a function of the proliferative capability of cancer cells, we investigated whether DNAJC15 expression may affect colony and spheroid formation." (PMID 39809321, 2025). "This iron-mediated unprogrammed cell death increases OC cells’ vulnerability to CDDP toxicity, unveiling that DNAJC15 may regulate an alternative anti-proliferative process besides apoptosis to prevent cancer cell growth." (PMID 39809321, 2025). "Besides, the DnaJC15 (second J-protein interacting partner of Magmas) levels were downregulated in response to chemotherapeutic reagents in cancer cells, thus imparting chemoresistance." (PMID 34715125, 2021).
DNAJC15 also shares sentences with these, for which no sentence is quoted: colitis (4 papers); Insulin resistance (2); Liver Disease (2); non-alcoholic fatty liver disease (2); non-alcoholic steatohepatitis (2); ulcerative colitis (2); alcohol (1); alcoholic hepatitis (1); cholestasis (1); Cholestatic liver disease (1); Chronic colitis (1); clear cell renal cell carcinoma (1); colon adenocarcinoma (1); colorectal cancer (1); COVID-19 (1); dilated cardiomyopathy (1); fibrosis (1); infection (1); intestinal inflammation (1); leukemia (1); liver (1); liver failure (1); liver fibrosis (1); malignant pediatric tumors (1); neuroblastoma (1); neurodegenerative disease (1); steatosis (1); uterine cancer (1); Wilms tumor (1).